NLRP3 (NLR family pyrin domain containing 3)
Diseases named in the same sentence as NLRP3 in open-access papers (continued):
Sharing a sentence is not in itself a finding about the gene and the disease.
Hyperglycemia (continued). "Our findings indicated that kakonein exerts a protective effect on hyperglycaemia‐induced chronic vascular disease by regulating the NLRP3 inflammasome through autophagy." (PMID 34180143, 2021). "Hyperglycemia-induced ROS (reactive oxygen species) overproduction is a major contributor to chronic low-grade inflammation, the activated NLRP3 inflammasome becoming a key in the pathogenesis of metabolic disturbances characteristic for CMS." (PMID 33172097, 2020). "In conclusion, these results showed that hyperglycemia induced NLRP3 inflammasome activation by inhibiting AMPK/mTOR‐mediated autophagy activation in KCs in TAA‐induced acute liver injury." (PMID 31625631, 2020). "Former studies testified that hyperglycaemia stimulated ATP secretion in renal resident cells, especially that accumulated extracellular ATP (eATP) can combine with P2X receptors and activate NLRP3 inflammasome in DKD." (PMID 32992874, 2020). "A similar behavior was seen in cardiomyocytes: hyperglycemia increased expression of NLRP3 and MyD88 in a way that is sensitive to empagliflozin or shifting from high glucose to low glucose." (PMID 33096896, 2020). "This view is supported by the finding that chronic hyperglycemia induced the upregulation of the oxidative sensor and NLRP3 modulator TXNIP, with consequent activation of inflammatory signaling pathways in both glial and microvascular endothelial cells." (PMID 32751658, 2020). "In conclusion, ELF3 interacted with SET8 to modulate MARK4 expression, which participated in hyperglycaemia-mediated endothelial NLRP3 inflammasome activation." (PMID 32439949, 2020). "In this study, we evaluated the role of hyperglycemia in regulating NOD‐like receptor family pyrin domain‐containing 3 protein (NLRP3) inflammasome activation by inhibiting autophagy induction in KCs in the TAA‐induced liver injury model." (PMID 31625631, 2020). "Our results demonstrated that hyperglycemia induced NLRP3 inflammasome activation by inhibiting mTOR‐mediated autophagy in KCs in TAA‐induced acute liver injury." (PMID 31625631, 2020). "The presented study provides new insights into understanding the mechanisms of NLRP3 inflammasome-regulated vascular calcification in HASMCs under hyperglycemia conditions." (PMID 31938471, 2020). "Previous in vivo and in vitro studies showed that hyperglycemia increases the expression of NLRP3 and activates caspase-1, inducing the release of IL-1β and IL-18." (PMID 32471207, 2020). "Several previous studies had established a prominent role for TXNIP in mediating retinal NLRP3-inflammasome activation in other models of type-1 diabetes, hyperglycemia and retinal neurotoxicity." (PMID 32492941, 2020). "Hyperglycemia during treatment with ipilimumab increased cardiotoxicity and reduced mortality of breast cancer cells in a manner that is sensitive to NLRP3." (PMID 33096896, 2020). "In the present study, we found that hyperglycemia significantly increased NLRP3 inflammasome activation and inhibited KC autophagy in TAA‐treated mice." (PMID 31625631, 2020). "In contrast, accumulating data has highlighted the importance and regulation of NLRP3 inflammasome activation and subsequent IL-1β secretion in hyperglycemia." (PMID 31938471, 2020). "On the other hand, the use of the anti-inflammatory compounds such as cepharanthine and piperine in a rat model of DN ameliorated hyperglycemia and renal dysfunction, and also decreased NLRP3 and NF-κB expression in diabetic kidneys." (PMID 32471207, 2020). "Our findings demonstrated that hyperglycemia aggravated TAA‐induced acute liver injury by promoting liver‐resident macrophage NLRP3 inflammasome activation via inhibiting AMPK/mTOR‐mediated autophagy." (PMID 31625631, 2020). "Hyperglycaemia can stimulate NLRP3 inflammasome activation in multiple cell types, including THP-1-derived macrophages, 3T3-L1 mature adipocytes and human adipose tissue." (PMID 32545355, 2020).
Hyperglycemia (continued). "During the progression of DKD, oxidative stress, hyperglycaemia and other factors are the upstream stimuli to promote the NLRP3 inflammasome assembling in different renal resident cells." (PMID 32992874, 2020). "Metabolic insults, including SFAs, pro-inflammatory adipokines, hyperglycemia and endotoxemia, represent major stimuli of NLRP3 inflammasome activation, and subsequent IL-1β production, in adipose tissue." (PMID 32545355, 2020). "In this study, we demonstrated that hyperglycemia reduces ipilimumab-related anticancer functions and enhances its cardiotoxicity in cellular models through mechanisms mediated by MyD88 and NLRP3 signaling." (PMID 33096896, 2020). "In DCM, hyperglycemia-induced ROS generation leads to cardiomyocyte pyroptosis and myocardial inflammation via activating the NLRP3 inflammasome." (PMID 31886288, 2019). "In conclusion, in our study, ALDH2 can protect the H9C2 cardiac cells against hyperglycemia-induced inflammation by suppressing the production of mitochondrial oxygen free radicals and stimulating NLRP3 inflammasome activation." (PMID 31871948, 2019). "In the diabetic heart, the NLRP3 inflammasome responds to hyperglycemia-induced toxicity and initiates the progression of pyroptosis." (PMID 31886288, 2019). "Hyperglycemia is also shown to stimulate the expression of NLRP3, resulting in increased secretion of cytokines IL-1β and IL-18." (PMID 31281401, 2019). "Hyperglycemia, fatty acids, and oxidative stress activate NLRP3 and caspase-1-mediated inflammasome, and inhibition of NLRP3 mitigates DMCM in diabetic rats." (PMID 31835893, 2019). "In this study, we evaluated NLRP3 inflammasome in a double transgenic mouse model, Akimba (Ins2AkitaxVEGF+/−), which demonstrates hyperglycemia, vascular hyperpermeability and neovascularization seen in the proliferative DR." (PMID 29434227, 2018). "A hydrolysate prepared by bovine casein attenuated nod-like receptor protein 3 (NLRP3) activity and improved insulin signaling, resulting in reduced hyperglycemia and inflammation in mice fed with HFD." (PMID 29473848, 2018). "Our results are consistent with previous findings that NLRP3 inflammasome can be activated by hyperglycemia in cultured mouse vascular endothelial cells or human umbilical vein endothelial cells." (PMID 29207644, 2017). "Meanwhile, therapeutic effects of IL-22 gene therapy were apparent despite initiation of treatment 17 weeks after persistent hyperglycemia and nephropathy onset, reflecting at least partial disease reversal by targeting renal NLRP3 inflammasome." (PMID 28726774, 2017). "In conclusion, hyperglycemia and hyperlipidemia can lead to the activation of NLRP3 inflammasomes, and their downstream molecules, including caspase-1, IL-1β, and IL-18, in the glomerular mesangium." (PMID 28708885, 2017). "Here, we review the molecular mechanism(s) of NLRP3 inflammasome activation in response to hyperglycemia in DCM." (PMID 28790925, 2017). "Our previous study demonstrated that hyperglycemia, a hallmark characteristic of T2DM, induced NLRP3 inflammasome-dependent caspase-1 activation and IL-1β maturation in human monocytic cells." (PMID 28970837, 2017). "So, the NLRP3 inflammasome pathway can be synergistically activated by hyperglycemia and AS, with consequently increased mRNA expression of NLRP3, ASC and caspase-1." (PMID 29151018, 2017). "During hyperglycemia and hypercholesterolemia, NLRP3 initiates or amplifies diverse downstream signaling pathways and drives pro-inflammatory processes, leading to cellular damage, such as autophagy and pyroptosis." (PMID 28708885, 2017). "Recent work demonstrated that TXNIP induced NLRP3 expression, activation of caspase-1, and release of IL-1β in a model of hyperhomocysteinemia or hyperglycemia with podocyte injury." (PMID 27867451, 2016).
Hyperglycemia (continued). "In conclusion, we demonstrated that TRPM2 was a Ca2+ mediator of hyperglycemia-induced ROS production and NLRP3 inflammasome activation through cooperatively interaction with p47 phox, and regulation of TXNIP in human monocytes." (PMID 27731349, 2016). "On the other hand, the innate immune response to chronic hyperglycemia by IL-1β, NLRP3 and caspase-1 inflammasome is cyclical." (PMID 22474421, 2012). "ICA was associated with reduced mtROS, cytosolic mtDNA, NLRP3 inflammasome activation, and pyroptosis in the hearts of DCM mice or hyperglycaemia-induced H9c2 cardiomyoblasts, which may occur in a SIRT3-dependent manner." (PMID 42292806, 2026). "They imply that RPE cellular impairment stems from chronic hyperglycemia‐induced glycolytic dysregulation, which fosters high lactic acid production, triggers histone lactylation of Txnip, activates the Txnip/Nlrp3 signaling cascade, and eventually instigates PANoptosis." (PMID 40959205, 2025). "NLRP3 is well known to be responsible for the chronic inflammation triggered by hyperglycemia." (PMID 41465472, 2025). "Critically, in diabetic pathologies, the BSP accelerates refractory wound repair by suppressing hyperglycemia-induced NLRP3 inflammasome activation (TXNIP/NLRP3/caspase-1 pathway), reducing macrophage-derived IL-1β secretion, and improving endothelial insulin sensitivity." (PMID 41268444, 2025). "Hyperglycemia represents a potent stimulis for the NLRP3 inflammasome." (PMID 40079000, 2025). "Additionally, hyperglycemia-induced mitochondrial ROS overproduction facilitates NLRP3 inflammasome activation, resulting in caspase-1-dependent maturation and the release of IL-1β." (PMID 41321403, 2025). "Thus, autophagy inhibits NLRP3 and prevents NLRP3-driven inflammatory responses in the Leydig cells during hyperglycemia." (PMID 40940788, 2025). "In addition, hyperglycemia and hyperlipidemia directly exacerbate mitochondrial oxidative stress and proinflammatory cytokine production, thus inducing the formation of NLRP3 inflammasome." (PMID 39021834, 2024). "Additionally, mangiferin decreased NLRP3 inflammasome activation and reactive oxygen species accumulation in hyperglycemia exposed macrophages." (PMID 39456979, 2024). "Moreover, GLP-1Ras protect against hyperglycemia-induced autoinflammatory damage by inhibiting the formation of the NLR family pyrin domain-containing 3 (NLRP3) inflammasome, thus providing anti-pyroptotic protection to cardiomyocytes." (PMID 39518550, 2024). "In fact, chronic hyperglycemia may induce the secretion of IL-Ι β via the activation of the NLRP3 inflammasome facilitated by the production of ROS and thioredoxin-interacting protein (TXNIP)." (PMID 38916735, 2024). "Hyperglycemia significantly increased the colocalization of NLRP3 with Caspase-1 in the glomeruli of db/db mice compared to control mice, indicating the formation of NLRP3 inflammasomes in diabetic mice." (PMID 37540330, 2023). "Moreover, 6-shogal, the most potent ginger-derived compound, displayed positive effects by reducing Akt activation, ROS production and NLRP3 inflammasome activation, thereby alleviating hyperglycemia-induced calcification of arterial smooth muscle cells." (PMID 37175869, 2023). "Both in vitro and in vivo, NLRP3 promoted hyperglycemia-induced endothelial inflammation." (PMID 37175869, 2023). "Despite inconsistent published results, it is becoming evident that TXNIP, another redox signaling regulator, is significantly increased in response to hyperglycemia and may act as a direct ligand of the NLRP3 inflammasome." (PMID 37175869, 2023). "The authors hypothesized that the activation of the PKM2-mediated NLRP3 inflammasome through hyperglycemia could potentially enhance plaque vulnerability." (PMID 37763063, 2023). "Moreover, hyperglycaemia can promote chronic low‐grade inflammation mediated by the Nlrp3 inflammasome, contributing to the pathogenesis of DM and its complications." (PMID 37621124, 2023).
Hyperglycemia (continued). "Islet cells exposed to chronic hyperglycemia will activate NLRP3 and induce IL-1β secretion." (PMID 37762961, 2023). "The P2X7/NLRP3 pathway plays an essential role in amplifying inflammation via an ATP feedback loop, promoting the inflammatory response, pyroptosis, and apoptosis of RECs in the early stages of diabetic retinopathy induced by hyperglycemia and inflammation." (PMID 35410316, 2022). "Interestingly, hyperglycemia has been reported to activate NLRP3 inflammasomes and downstream effector inflammatory cytokines, including TNF-α and IL-1β, which are believed to induce programmed proinflammatory cell death (pyroptosis)." (PMID 35453376, 2022). "Hyperglycemia also leads to the activation of NLRP3 inflammasome." (PMID 34904398, 2022). "In addition, previous studies have revealed that spleen tyrosine kinase (Syk) is involved in hyperglycemia-induced activation of the Syk/JNK/NLRP3 signaling pathway in rat glomerular thylakoid cells and HK2 cells." (PMID 35126159, 2022). "In the present study, we demonstrated that BBR could ameliorate renal tubulointerstitial fibrosis by inhibiting hyperglycemia-induced EMT via inactivation of NLRP3 inflammasome both in vivo and in vitro." (PMID 35618411, 2022). "Persistent hyperglycemia, with increased glycolysis, can lead to mitochondrial dysfunction, which induce overproduction of mitochondrial ROS (mt-ROS), which in turn activates the NLRP3 inflammasome." (PMID 35844498, 2022). "It was suggested that peroxynitrite could activate NLRP3 inflammasome in hyperglycemia, a mediator in HT following reperfusion." (PMID 34054705, 2021). "It was also found that continuous hyperglycemia could activate the NLRP3 inflammatory body, promote the release of IL-1β and IL-18, and eventually lead to the occurrence and progression of DKD." (PMID 34007404, 2021). "In conclusion, this study reported for the first time that kakonein has a significant cardiovascular protective effect, which is reflected in the restoration of endothelial junctions by inhibiting the NLRP3 inflammasome through activation of autophagy in hyperglycaemia." (PMID 34180143, 2021). "However, most studies on diabetes-related diseases and the NLRP3 inflammasome have been performed under constant hyperglycemia." (PMID 34576117, 2021). "In addition, kakonein inhibited both hyperglycaemia‐induced cardiovascular endothelial junction dysfunction and NLRP3 inflammasome activation, similar to autophagy agonist." (PMID 34180143, 2021). "The other components of MetS except hyperglycemia also showed this trend in females, at least for the univariate model, which suggested increasing hypertriglyceridemia and hypertension with higher tertiles of NLRP3 levels." (PMID 34362072, 2021). "Thus, targeting the excessive activation of the NLRP3 inflammasome induced by HG under hyperglycemia conditions represent a promising strategy for the treatment of DFU." (PMID 33981238, 2021). "Hence, UCP2 is likely an upstream mediator of ROS generation and NLRP3 inflammasome activation after hyperglycemia-exacerbated I/R damage." (PMID 33735403, 2021). "Hence, the mechanism of kakonein in hyperglycaemia‐induced endothelial dysfunction through NLRP3 inflammasome needs to be further explored." (PMID 34180143, 2021). "Meanwhile, sustained hyperglycemia, increased glycolysis and saturated fatty acids like palmitic acid will also lead to impaired autophagy and mitochondrial dysfunction, which induce mROS overproduction--the second signal activating the NLRP3 inflammasome." (PMID 34631209, 2021).
Hyperglycemia (continued). "In the present study, we hypothesized that ELF3 may increase MARK4 expression, thus playing a crucial role in hyperglycaemia-induced NLRP3 inflammasome activation in vascular endothelial cells." (PMID 32439949, 2020). "Microtubule affinity regulating kinase 4 (MARK4) has been reported to play a crucial role in the regulation of NLRP3 inflammasome activation and may be a potential target for hyperglycaemia-mediated NLRP3 inflammasome activation and endothelial inflammation." (PMID 32439949, 2020). "Besides, by blocking early inflammatory mediators as NLRP3 inflammasome components induced by hyperglycemia will represent the excellent targets to prevent T2D and its complications like DCM." (PMID 33172097, 2020). "NLRP3 was involved in hyperglycemia-induced endothelial inflammation, both in vitro and in vivo." (PMID 32751658, 2020). "Based on this scenario, overexpression of NLRP3/MyD88 and cytokines during hyperglycemia in breast cancer cells and cardiomyocytes could be a key player in cardiotoxicity and resistance to ipilimumab." (PMID 33096896, 2020). "Hyperglycemia-induced ROS production may stimulate NLRP3 inflammasome activity through different pathways, including thioredoxin (TRX1)-TXNIP dissociation and accumulation of AGEs and advanced lipoxidation endproducts (ALEs)." (PMID 32751658, 2020). "However, NLRP3 and cleaved caspase-1 complex formation increased with hyperglycemia and cytokine challenge but was inhibited by tonabersat treatment." (PMID 33396676, 2020). "The NLRP3 inflammasome is activated by oxidative stress and hyperglycemia in DN." (PMID 32566101, 2020). "In particular, inhibition of NLRP3 inflammasome could prevent facilitation of the progression of hyperglycemia-induced renal failure." (PMID 32050658, 2020). "Hyperglycemia induces the oxidative reaction and releases ROS, as well as activating the subsequent NLRP3 inflammasome signaling, resulting in injury of podocytes or tubular cells and mesangial cell proliferation, leading to the occurrence and development of DN." (PMID 31485193, 2019). "In an excellent agreement, the present data revealed that hyperglycemia could induce the activation of the NLRP3 inflammasome and ultimately lead to the increased expression of IL-1β and IL-18." (PMID 31178664, 2019). "Hyperglycemia can activate the NLRP3 inflammasome and mediate the inflammatory response of patients with DKD by ATP-P2X4 signaling, suggesting that this pathway may serve as an anti-inflammatory therapeutic target for delaying DKD." (PMID 29929501, 2018). "In vivo and in vitro analyses indicated that NGR1 could inhibit hyperglycemia induced oxidative stress and NLRP3 inflammasome activation through activating the Akt/Nrf2/HO-1 pathway in hippocampal neurons." (PMID 29507694, 2018). "In addition, in metabolic stress conditions, such as hyperglycemia and hyperlipidemia, NLRP3 combines with ASC and procaspase-1 to form activated NLRP3 inflammasome." (PMID 28928791, 2017). "Moreover, blocking early inflammatory mediators such as TXNIP (as well as NLRP3 inflammasome components) that significantly induced by hyperglycemia will represent the excellent targets to prevent diabetes and its complications DCM." (PMID 28790925, 2017). "Reactive oxygen species (ROS) induced by sustained hyperglycemia in renal tissues may directly or indirectly activate nucleotide binding and oligomerization domain—like receptor family pyrin domain-containing 3 (NLRP3) inflammasome." (PMID 28182085, 2017). "In conclusion, hyperglycaemia-induced NLRP3 inflammasome activation may be a ROS-dependent process in pyroptotic cell death, and NLRP3 inflammasome-induced pyroptosis aggravates MI/R injury in diabetic rats." (PMID 29062465, 2017). "Therefore, our results supported that TRPM2 represented a potential therapeutic target for ameliorating NLRP3 inflammasome activation related to hyperglycemia-induced oxidative stress in T2DM." (PMID 27731349, 2016).